CR2 (complement C3d receptor 2)
Description:
Serves as a receptor for various ligands including complement component CD3d, HNRNPU OR IFNA1. When C3d is bound to antigens, attaches to C3d on B-cell surface and thereby facilitates the recognition and uptake of antigens by B-cells. This interaction enhances B-cell activation and subsequent immune responses. Forms a complex with several partners on the surface of B-cells including CD19, FCRL5 and CD81, to form the B-cell coreceptor complex that plays a crucial role in B-cell activation and signaling. Also induces specific intracellular signaling separately from the BCR and CD19 by activating the tyrosine kinase SRC, which then phosphorylates nucleolin/NCL and triggers AKT and GSK3 kinase activities in a SYK/CD19-independent manner. Acts as a ligand for CD23 (FcepsilonRII), a low-affinity receptor for IgE, which is expressed on B-cells and other immune cells, and thus participates in the regulation of IgE production. (Microbial infection) Acts as a receptor for Epstein-Barr virus.
Synonyms: CD21; C3DR; CR; CVID7; SLEB9
Tractability: Antibody: UniProt places it where antibodies can reach, with high confidence; its Gene Ontology location is reachable by antibodies, with high confidence; UniProt predicts a signal peptide or a membrane-spanning region. PROTAC: its protein half-life has been measured.
Gene: Protein-coding gene on chromosome 1 (207,453,024 to 207,489,895, forward strand). Ensembl gene ENSG00000117322.
Subcellular location: Cell membrane
Pathways (Reactome):
Immune System: Regulation of Complement cascade
Gene Ontology:
Molecular function: complement binding; DNA binding; immunoglobulin receptor binding; protein binding; protein homodimerization activity; receptor ligand activity; transmembrane signaling receptor activity; complement receptor activity; virus receptor activity
Biological process: B cell activation; B cell differentiation; B cell proliferation; complement activation, alternative pathway; symbiont entry into host cell; type I interferon-mediated signaling pathway; immune response; negative regulation of complement activation, classical pathway; T cell mediated immunity; complement receptor mediated signaling pathway
Cellular component: extracellular exosome; plasma membrane; receptor complex; membrane
Genetic constraint (gnomAD): Loss-of-function variants: 83 observed, 114.39 expected, observed/expected ratio (o/e) 0.73, 90% interval 0.61 to 0.87. The upper end of that interval is the gene's LOEUF score, 0.87, which puts it in group 3 of 6, group 1 being the genes least tolerant of losing a copy. Missense variants: 1,200 observed, 1,351.6 expected, observed/expected ratio (o/e) 0.89, 90% interval 0.85 to 0.93. Synonymous variants: 465 observed, 470.15 expected, observed/expected ratio (o/e) 0.99, 90% interval 0.92 to 1.07.
Gene-disease validity (ClinGen):
ClinGen rates the evidence that CR2 causes each of these diseases.
immunodeficiency, common variable, 7 (autosomal recessive): Definitive.
Homologues: Orthologues: chimpanzee CR2 (94% identical), macaque CR2 (93% identical), rabbit CR2 (66% identical), mouse Cr2 (63% identical), rat Cr2 (62% identical), guinea pig CR2 (57% identical), zebrafish csmd2 (23% identical), tropical clawed frog c4bpa (10% identical). Paralogues in human: CR1 (29% identical), CSMD3 (28% identical), CSMD2 (27% identical), CSMD1 (27% identical), SVEP1 (25% identical), C4BPA (16% identical), CR1L (13% identical), SELP (13% identical), SEZ6L (12% identical), CFH (11% identical), SEZ6L2 (11% identical), SELE (10% identical), and 27 more.
Diseases named in the same sentence as CR2 in open-access papers:
CR2 is named in the same sentence as 207 diseases in open-access papers, as found by Europe PMC text mining. Sharing a sentence is not in itself a finding about the gene and the disease. The quoted sentences say what the papers report.
systemic lupus erythematosus (34 papers, 2008 to 2025). An autoimmune multi-organ disease typically associated with vasculopathy and autoantibody production. "However, probably the most compelling evidence to link CR2 function to the onset of lupus arose from a study of lupus susceptibility loci in the NZM2410 mice." (PMID 19187965, 2009). "Variations or deletions of the CR2 gene in humans or in mice are associated with a variety of autoimmune and inflammatory conditions, such as systemic lupus erythematosus (SLE) and chronic variable immunodeficiency (CVID)." (PMID 31011487, 2019). "Additionally, we explored the association of CR2 polymorphisms with clinical manifestations of lupus in order to generate new hypotheses regarding how CR2 contributes to disease development." (PMID 25180293, 2016). "Indeed, data generated using mice deficient in the Cr2 gene (encoding both mouse CR1 and CR2 through alternative splicing; Cr2−/−), appeared to confirm that both these proteins were important in the development of auto-antibodies in lupus susceptible mice." (PMID 19187965, 2009). "CR2 encodes complement receptor 2 (CD21) and is a co-receptor on B cells, which play a central role in autoimmunity, such that patients with systemic lupus erythematosus show reduced CR2 levels." (PMID 36497424, 2022). "Here, we present a new mouse model expressing the human proteins CR1 and CR2 that will be of value to study of an array of human diseases including Alzheimer’s disease, Systemic Lupus Erythematosus and infections such as malaria." (PMID 32907542, 2020). "Moreover, haplotypes based on three CR2 SNPs (rs3813946, rs1048971, rs17615) were associated with an increased risk of developing systemic lupus erythematosus (SLE), underscoring the potential role of CR2 in this disease." (PMID 37833411, 2023). "A role for complement receptors CR2 and CR1 in the autoimmune disease, Systemic Lupus Erythematosus (SLE) is well established." (PMID 35769482, 2022). "The suggestion that complement receptor type 2 (CR2) expression levels might be important in autoimmune disease arose from two studies that noted a marked down regulation of CR2 expression levels on B lymphocytes isolated from patients with systemic lupus erythematosus (SLE)." (PMID 19187965, 2009).
lymphoma (31 papers, 2006 to 2025). A malignant (clonal) proliferation of B- lymphocytes or T- lymphocytes which involves the lymph nodes, bone marrow and/or extranodal sites. "Finally, within CSF + LM group, differential protein profiles were observed between leukemia and lymphoma (such as FCGR1, CR2, ABL1, PTPRC, SELP, ITGB1, COL9A3 or ITGAX), which could subtype the CSF + LM depending on the primary tumor." (PMID 35053611, 2022).
autoimmune disease (26 papers, 2008 to 2025). A disorder resulting from loss of function or tissue destruction of an organ or multiple organs, arising from humoral or cellular immune responses of the individual to their own tissue constituents. "RCA members, such as complement receptor 2 (CR2), are well-established susceptibility genes in complex autoimmune diseases." (PMID 35769482, 2022). "CR2, the gene that encodes the complement receptor type 2, has been previously shown to decline with age in B-cells and is associated with ischemic stroke, autoimmune disease, and chronic infection." (PMID 37924441, 2024). "CR2 mutations may be associated with a type of AR common variable immunodeficiency and autoimmune diseases due to the impairment of self-tolerance." (PMID 36834577, 2023). "TT30 is an FH and CR2 fusion protein that has been designed to selectively inhibit the AP locally at activation sites in order to minimize the risk of infection or autoimmune disease which could increase upon systemic complement inhibition." (PMID 33362763, 2020). "The functions of CR1 and CR2 on T cells remain to be determined, but we note that CR2 is the receptor for Epstein-Barr virus, which is a cause of T cell lymphomas and a candidate environmental factor in autoimmune disease." (PMID 28814669, 2017). "The involvement of complement receptor 2 (CR2) in B cell tolerance and autoimmune disease has been revealed over the past decade or so." (PMID 19187965, 2009). "There is a growing body of evidence that CR1/CR2 plays an important role in maintaining and defining normal B cell function and thereby helps to prevent the onset of autoimmune disease (reviewed)." (PMID 19187965, 2009). "While complement receptor signaling on B cells typically helps regulate their activation, reduced receptor expression (e.g., CR2) in autoimmune diseases may impair this mechanism." (PMID 39768874, 2024). "Aberrant expression of CR2 on the surface of B cells has been demonstrated both in mouse models of the disease and SLE patients, which functionally contributes to B cell autoreactivity and autoimmune disease susceptibility." (PMID 35769482, 2022). "We propose that mAbs 7D18.1 and 7D323.1 can act as surrogate markers for CR1 and CR2, respectively, and that they may be useful tools for studying the immune complexes that are generated in various autoimmune diseases." (PMID 21070093, 2011). "Thus, targeting the inhibitory CR1 and CR2 in autoreactive B cells could serve as a novel scenario for therapeutic options in autoimmune diseases." (PMID 39768874, 2024). "We have recently found evidence of alteration in tyrosine phosphorylation patterns in response to BCR and CR2/CD19 cross-linking in the hCR2high mice and demonstrated that these changes protect hCR2high mice from the onset of an organ specific autoimmune disease collagen-induced arthritis (CIA)." (PMID 19187965, 2009).
Autoimmunity (22 papers, 2015 to 2025). The occurrence of an immune reaction against the organism's own cells or tissues. "CR2 and CR1 modulate B-cell activation, and the roles of CR3 and CR4 are associated with autoimmune conditions." (PMID 39273179, 2024). "Alterations of CR2 expression have variable different effects on manifestations of disease in animal models of autoimmunity." (PMID 27446959, 2016). "Genetic variation, such as SNPs, in the BEN-2 region may influence expression of both CR2 and CD55 in tandem, thereby exacerbating the effect of variants in their contributions to autoimmunity." (PMID 35769482, 2022). "Human CR2 has been shown to bind DNA and chromatin in the absence of C3 opsonization, therefore, CR2 deficiency in SLE might also influence the development of autoimmunity in SLE through altered receptor interactions with DNA." (PMID 33644062, 2021).
COVID-19 (17 papers, 2020 to 2025). A disease caused by infection with severe acute respiratory syndrome coronavirus 2. "All three proteins enriched in lymphoid organs, i.e., STAB2, Leukocyte Immunoglobulin-Like Receptor B1 (LILRB1), and CR2, had decreased serum levels in COVID-19 patients." (PMID 37739942, 2023). "CD21 (complement receptor type 2, CR2), a co-receptor of the BCR, was also significantly down-regulated in severe COVID-19 patients." (PMID 32669287, 2020).
B-cell lymphoma (16 papers, 2008 to 2025). "CD21 (also known as complement receptor 2 [CR2] or B2) is also associated with at least some B-cell lymphomas but anti-CD21 antibody internalization has only been evaluated in a limited number of studies." (PMID 17991300, 2008). "The acute phase protein, SAA has been shown to be overexpressed in B-cell NHL associated with SIV infection in monkeys, and complement components (C3 and CR2) may be involved in lymphomagenesis and/or complement activation." (PMID 24922518, 2014). "CD19 and CD21 (CR2) are co-receptors found on B-cells and various B-cell lymphomas, including non-Hodgkin lymphoma." (PMID 17991300, 2008).
rheumatoid arthritis (14 papers, 2013 to 2025). A chronic, systemic autoimmune disorder characterized by inflammation in the synovial membranes and articular surfaces. "With regards to other models, CR2 engagement has been found to be essential for the development of the human rheumatoid arthritis (RA) model collagen-induced arthritis (CIA) and experimental autoimmune myocarditis." (PMID 40409177, 2025).
viral infection (13 papers, 2011 to 2025). "Among them, the gp350 protein is the most abundant glycoprotein on the surface of EBV virions and interacts with the complement receptor 2 (CR2/CD21) on B lymphocytes to trigger viral infection." (PMID 40338258, 2025).
sarcoma (9 papers, 2011 to 2025). A usually aggressive malignant neoplasm of the soft tissue or bone. "FDC sarcomas generally present the immunophenotype of normal FDCs, being positive for: CD21 (CR2), CD23 (Fc epsilon RII) and CD35 (CR1)." (PMID 33520702, 2020).
influenza (8 papers, 2010 to 2023). An acute viral infection of the respiratory tract, occurring in isolated cases, in epidemics, or in pandemics; it is caused by serologically different strains of viruses (influenzaviruses) designated A, B, and C, has a 3-day incubation period, and usually lasts for 3 to 10 days. "CR2 targeting complement inhibitors are used to treat mouse influenza viral pneumonia model, with PBS treatment group as the control." (PMID 20144216, 2010).
Arthritis (7 papers, 2009 to 2024). Inflammation of a joint. "Our previous studies have established that mice prematurely expressing human CR2 under the control of a lambda light chain promoter (in particular the hCR2high line) have a marked deficit in their immune response to various antigens and fail to develop collagen-induced arthritis." (PMID 19187965, 2009).
common variable immunodeficiency (6 papers, 2012 to 2024). "Additionally, SP1NK5, ITGA2B, and CR2 exhibit diverse implications, linking to Netherton syndrome, bleeding disorders, and common variable immunodeficiency, respectively." (PMID 38890201, 2024). "For example, individuals with common variable immunodeficiency (CVID, for example, associated with deletions in CD19, MS4A1 (CD20) and CR2 (CD21) that impair B cell function) have been found to be at increased risk of severe disease and require further study." (PMID 34352148, 2022).
HIV-1 infection (6 papers, 2014 to 2023). The type species of lentivirus and the etiologic agent of acquired immunodeficiency syndrome (AIDS). "CR2 encodes complement C3d receptor 2, which is the main receptor for complement protein C3d, plays an essential role in adaptive immune response, and is associated with susceptibility to HIV-1 infection in humans." (PMID 37134013, 2023).
multiple sclerosis (5 papers, 2013 to 2024). A progressive autoimmune disorder affecting the central nervous system resulting in demyelination. "Similarly, Werneburg and colleagues also used Crry, but fused it to a domain of CR2, which binds activated C3, in the context of multiple sclerosis." (PMID 38817607, 2024).
glioma (4 papers, 2019 to 2025). A benign or malignant brain and spinal cord tumor that arises from glial cells (astrocytes, oligodendrocytes, ependymal cells). "Additionally, six targets are regulated by our miRNAs both in glioma and meningioma: CR2, KNG1, PROS1, F9, MBL2 and F11, while different miRNAs are dysregulated in each cancer type." (PMID 32545233, 2020).
ischemic stroke (4 papers, 2015 to 2024). A stroke disorder caused by obstruction of blood flow to the brain, due to thrombotic (local blood clot formation) or embolic (due to a blood clot or other material traveling from another site) event. "The data presented here support the notion of a dual role for complement in ischemic stroke by comparing C3 deficiency with transient approaches of complement inhibition using CR2-Crry and CR2-fH." (PMID 26714866, 2015). "In regard to ischemic stroke, the role of CR2 in the brain has been scarcely investigated until now." (PMID 31011487, 2019). "CR2-mediated targeting obviates the need for systemic complement inhibition, and the current data indicate that CR2-fH does not increase susceptibility to infection following experimental ischemic stroke." (PMID 26714866, 2015). "Inhibiting all the pathways of complement activation via CR2-Crry treatment is not the best option for reducing complement-related ischemic brain injury because it affects the subsequent tissue regeneration after ischemic stroke." (PMID 31011487, 2019).
lung carcinoma (4 papers, 2022 to 2025). "Taking these findings into consideration, we evaluated the relationship between the CD21 (CR2) transcript expression in 1325 lung cancers vs. normal tissue." (PMID 35215076, 2022). "Given its limited prior research in lung cancer, we hypothesize that CR2 may serve as a novel therapeutic target." (PMID 40591103, 2025).
ovarian carcinoma (4 papers, 2020 to 2024). A malignant neoplasm originating from the surface ovarian epithelium. "Here, we have used two different oncolytic adenoviruses—the Ad5 E1A CR2-deletion mutant dl922-947 (group C) and the chimeric Ad3/Ad11p mutant enadenotucirev (group B)—to investigate the effect of NK cells on overall anti-cancer efficacy in ovarian cancer." (PMID 32195317, 2020).
periodontitis (4 papers, 2016 to 2022). An acute or chronic inflammatory process that affects the tissues that surround and support the teeth. "In accordance, molecules involved in B cell activation including CD79, CD19, Lyn, and CR2 were significantly increased in periodontitis tissue." (PMID 27531006, 2016).
Sepsis (4 papers, 2018 to 2025). Sepsis is defined as life-threatening organ dysfunction caused by a dysregulated host response to infection. "At the opposite end of the spectrum of IEI genes induced by sepsis, we found that the most reduced genes are those encoding Nlrp12 (40x), Cxcr2 (35x) and Cr2 (12x)." (PMID 41229427, 2025). "Finally, the NTCI peptide reversed the sepsis-induced suppression of the gene encoding the CR2 complement receptor that mediates complement activation through the alternative pathway." (PMID 41229427, 2025). "CR2-Crry, a complement inhibitor fusion protein consisting of CR2 and a CR1-related gene (Crry), showed increased survival and marginally affected serum complement levels in an intestinal I/R injury model of sepsis." (PMID 29899265, 2018).
lupus nephritis (3 papers, 2016 to 2025). Glomerulonephritis in the context of systemic lupus erythematosus. "CR2–fH reduces complement-mediated kidney injury in mouse models lupus nephritis and C3 glomerulopathy." (PMID 27199983, 2016).
myeloma (3 papers, 2011 to 2023). "These include adhesion molecules such as JAM2 and JAM3 as well as CR2, the latter of which was shown to play a role in the interaction of myeloma cells with the bone marrow stroma." (PMID 25188243, 2014).
nasopharyngeal carcinoma (3 papers, 2013 to 2023). A carcinoma arising from the nasopharyngeal epithelium. "Regarding CR2 polymorphisms, a previous study identified CR2 SNP rs3813946T/C as associated with increased susceptibility to nasopharyngeal cancer in the Cantonese ethnicity." (PMID 37833411, 2023). "A significant association of CR2 SNP (rs3813946) with the development of nasopharyngeal carcinoma was indicated in Cantonese population, and the genetic variations of complement system genes C5 and C9 plays a potential role in susceptibility to non-Hodgkin lymphoma (NHL)." (PMID 24621201, 2014).
pneumonia (3 papers, 2010 to 2025). An acute, acute and chronic, or chronic inflammation focally or diffusely affecting the lung parenchyma, caused by an infection in one or both of the lungs (by bacteria, viruses, fungi, or mycoplasma.). "The survival and lung tissue injury of the mice is observed and the effect of CR2 targeting complement inhibitors on pneumonia induced by influenza virus is evaluated." (PMID 20144216, 2010). "In our opinion, this is the first study to identify SNPs in antioxidant (SOD1, CAT, GPX1, NOS, HMOX1, and NQO1) and immunological (IL-1α, IL1B, IL6, TNF-α, IL10, LFA-1, CR2, IL17, IL13, DEFB123, SCART1, and ICAM1) genes as potential suspects for pneumonia resistance/susceptibility in Barki ewes." (PMID 40221769, 2025).